VDR (vitamin D receptor)
Diseases named in the same sentence as VDR in open-access papers (continued):
Sharing a sentence is not in itself a finding about the gene and the disease.
Hypertension (continued). "The purpose of this review is to summarize the vast amount of information regarding VDR polymorphisms and essential hypertension and discuss its possible role as diagnostic tools." (PMID 36788562, 2023). "Many studies have linked VDR gene polymorphism with essential however some studies have focused on the triangular relationship of vitamin D, VDR polymorphism, and essential hypertension, but the results of these studies were conflicting." (PMID 36788562, 2023). "In the evaluation of the VDR polymorphisms, it was observed that the CC genotype (recessive model) of the SNP rs7975232 was significantly associated with hypertension (OR = 5.91, 95% CI = 1.91–18.32, p = 0.002)." (PMID 36364874, 2022). "Consistent with the results of previous studies, our results demonstrated an association between a VDR variant and an almost 6-fold increase in the risk of hypertension." (PMID 36364874, 2022). "Similar to VDR mutant mice, 1α-hydroxylase knockout mice also presented with hypertension and cardiac hypertrophy that was associated with upregulation of the RAAS in cardiac and renal tissue." (PMID 36501215, 2022). "A recent meta-analysis further underlines the relationship between VDR polymorphisms and increased susceptibility to hypertension." (PMID 34070202, 2021). "The results in our study reveal that the VDR BsmI polymorphism is closely associated with predisposition to higher hypertension." (PMID 34574039, 2021). "The authors suggested that the population carrying the VDR BsmI AA genotype has a lower hypertension risk than those carrying the GA or GG genotype." (PMID 34578994, 2021). "It makes this study valuable in the discussion about the pivotal role of VDR genetic variants in pathogenesis of hypertension in pregnancy in a particular European population and undoubtedly constitutes the strength of the study." (PMID 34574039, 2021). "The association between PE and VDR BsmI polymorphism occurrence persisted even after adjustment for the pre-pregnancy BMI value as a predisposing factor for hypertension in pregnancy." (PMID 34574039, 2021). "A correlation between the VDR BsmI polymorphism with systolic and diastolic blood hypertension was noted." (PMID 34574039, 2021). "In this study, we found that myeloid-specific VDR deficiency is sufficient to induce high blood pressure in mice with adequate vitamin D status." (PMID 32968066, 2020). "Mice with deficiency of VDR (Vdr-/-) have increased levels of renin and consequently of AngII, resulting in hypertension and cardiac hypertrophy, lipid metabolism, cellular stress response, and changes in the vascular function." (PMID 31623356, 2019). "LRAT expression level increased accompanying with the increase of VDR expression level in children with hypertension, suggesting VA associated with 25(OH)D in the blood pressure regulation process which need further research in future." (PMID 30631592, 2018). "This variant lies within vitamin D receptor (VDR), whose 6 out of 9 transcripts were found to be affected with LoF mutation, and is associated with many disease conditions including the hypertension." (PMID 29420653, 2018). "There is a strong association between common VDR polymorphisms, as e.g., BsmI and FokI, and hypertension risk outside pregnancy." (PMID 29113124, 2017). "FokI polymorphism of VDR influences plasma renin activity and seems to be associated with a decreased risk of hypertension." (PMID 29113124, 2017). "Recently, a prospective study has been carried out which aimed to evaluate the association of circulating vitamin D metabolites, VDR FokI and BsmI gene polymorphisms, and their interaction with risk of hypertension." (PMID 26000281, 2015). "The prevalence of the VDR BsmI polymorphism and its association with anthropometric and biochemical features of metabolic syndrome, including high blood pressure, were examined in 351 randomly selected healthy postmenopausal women." (PMID 23049672, 2011).
Hypertension (continued). "However, it was observed that VDR gene polymorphisms do have a clear association with hypertension susceptibility, as evidenced by the significantly higher occurrence of FokI genotypic variants in hypertensive patients." (PMID 38483874, 2024). "However, the reported roles of VDR variants in hypertensive disorders are inconsistent among different populations." (PMID 38530345, 2024). "Due to the importance of the association between hypertension and Fok I polymorphism, we performed a review to find out whether this SNP of VDR gene plays a protective role in hypertension or should be considered as a risk factor for the onset of the disease." (PMID 36788562, 2023). "Observational evidence supports the concept that vitamin D plays a role in the pathogenesis of cardiovascular disease and arterial hypertension which is further supported by meta-analysis and case control studies reporting how VDR polymorphism leads to the onset and development of hypertension." (PMID 36788562, 2023). "A meta-analysis study has indicated Fok I polymorphism of the VDR gene results in formation of a truncated protein that evidently increases the synthesis of renin and angiotensin II, thereby promoting the development of hypertension." (PMID 36788562, 2023). "The findings of the studies support the hypothesis that VDR (Fok I and Bsm I) polymorphisms may be associated with susceptibility to essential hypertension." (PMID 36788562, 2023). "More research with larger samples is needed after removing confounding factors to determine whether VDR gene polymorphism is protective or a risk factor for the development of essential hypertension." (PMID 36788562, 2023). "Furthermore, the CC genotype (recessive model) of the rs7975232 VDR polymorphism was significantly associated with a risk of hypertension (OR = 5.91, 95%CI = 1.91–18.32, p = 0.002)." (PMID 36364874, 2022). "Furthermore, we observed that both the rs10741657 and rs2060793 polymorphisms of the CYP2R1 can significantly influence glucose metabolism, while the rs7975232 polymorphism of the VDR was significantly associated with the risk of hypertension." (PMID 36364874, 2022). "Mice lacking VDR specifically in the endothelium were able to shed more light on the question whether hypertension in global VDR knockout mice is caused by RAAS activation or is independent of RAAS." (PMID 36501215, 2022). "We tested the hypothesis that impaired vitamin D signaling in macrophages causes hypertension using conditional knockout of the myeloid vitamin D receptor in mice (KODMAC)." (PMID 32968066, 2020). "Accordingly, VDR-deficient mice display high renin and AngII levels and develop hypertension." (PMID 31623356, 2019). "Moreover, VDR gene polymorphisms (BsmI, ApaI, and FokI) have been shown to be associated with left ventricle hypertrophy, atherosclerosis, and essential hypertension." (PMID 26000281, 2015). "All the mechanisms discussed play a role in developing hypertension as well as polymorphism in the VDR gene which binds to high-affinity receptors mediates the biological activities of 1,25(OH)2D3, and polymorphisms in the gene encoding the VDR appear to predispose the onset of hypertension." (PMID 36788562, 2023). "It has been shown that these genetic changes in the VDR can significantly reduce the effectiveness of vitamin D action; thus, contributing to the development of several cardiovascular diseases, in particular, the Bsm I-B allele has been strongly associated with hypertension." (PMID 36788562, 2023). "Moreover, the decoupling between Hsp70 and VDR associated with a possible poor expression of WT-1 could be keys to hypertension development." (PMID 27009470, 2016). "For instance, vitamin D/VDR deficiencies are correlated with cardiovascular disease, bone defects, and a whole variety of inflammatory diseases, and vitamin D-deficient individuals have higher risk of developing cardiac hypertrophy, hypertension, and myocardial infarction." (PMID 27145372, 2016).
Hypertension (continued). "Renin expression and plasma angiotensin II production were found to be increased in vitamin D receptor-null (VDR-null) mice, leading to hypertension, cardiac hypertrophy and increased water intake." (PMID 41517402, 2025). "Experimental studies, for instance, have shown that vitamin D receptor (VDR) knockout mice develop arterial hypertension when compared to control groups, presumably due to heightened plasma renin levels leading to secondary RAAS activation." (PMID 41516172, 2025). "Furthermore, other environmental and genetic determinants, such as dietary vitamin D intake, sunlight exposure, physical activity, and vitamin D receptor (VDR) polymorphisms, may also influence maternal 25(OH)D levels and susceptibility to hypertensive disorders of pregnancy." (PMID 41301719, 2025). "Other studies with VDR knockout mice showed stimulation of the renin–angiotensin–aldosterone system favoring hypertension, increased fluid intake, and left ventricular hypertrophy." (PMID 39267468, 2024). "The association between Vitamin D Receptor (VDR) gene polymorphisms and essential hypertension (EH) remains controversial." (PMID 39715198, 2024). "Since the VDR is widely distributed in vascular endothelial cells, vascular smooth muscle cells and cardiomyocytes, the role of vitamin D and VDR in hypertension has received extensive attention." (PMID 36788562, 2023). "We observed a decrease in the expression of the nephrogenic gene, wt-1, and VDR by week 4, before the establishment of arterial hypertension, suggesting that the alteration in the kidney occurs previous to the increase in blood pressure." (PMID 36771473, 2023). "Studies conducted that focused on hypertension in mice showed the development of high blood pressure and cardiac hypertrophy linked to increased RAAS activation in VDR knock-out mice." (PMID 37571241, 2023). "The frequency of VDR Bsm I AA genotype decreased in hypertension patients compared with healthy controls." (PMID 36788562, 2023). "Several studies have reported mixed results with respect to relationship of VDR gene and hypertension." (PMID 36788562, 2023). "1α-hydroxylase knockout mice have a similar phenotype compared with global VDR knockout mice, making them a useful tool to investigate the role of the VDR in hypertension." (PMID 36501215, 2022). "Briefly, VDR deletion results in elevated production of renin and angiotensin II, leading to hypertension and cardiac hypertrophy." (PMID 33809311, 2021). "As a result of increased renin level, angiotensin II increased and lead to the development of hypertension and cardiac hypertrophy in vitamin D receptor null mice." (PMID 34946242, 2021). "In mice, germline vitamin D receptor (VDR) knockouts exhibit hypertension and cardiac hypertrophy due to upregulation of renin promoter activity and RAS activation." (PMID 32968066, 2020). "VDR null-mice exhibited increased concentrations of renin and angiotensin II leading to hypertension." (PMID 32164233, 2020). "Vitamin D has many pleiotropic effects on body homeostasis, such as cardio-protective and neuro-protective functions, hypertension control and is also involved in antitumor activity as well as immunomodulation through the Vitamin D receptor (VDR)." (PMID 32204545, 2020). "ANGII is a powerful vasoconstrictor whose increase also leads to the development of hypertension and cardiac hypertrophy in VDR-null mice." (PMID 31426337, 2019). "This review discusses the role of the RAS, its relationship with hypertension, vitamin D, VDR, VDD, and the immune system that provide a microenvironmental niche in regulating the ESC-like cells within the KALTs." (PMID 32039229, 2019). "Increased RAS activity by a VDR-mediated effect leads to increased renin levels, resulting in increased plasma ATII levels which cause hypertension in mice." (PMID 32039229, 2019).
Hypertension (continued). "This study demonstrated that serum LRAT strongly correlated with blood pressure in children, and the serum 25(OH)D and its receptor VDR in children with hypertension were lower than those in the control group." (PMID 30631592, 2018). "For example, the high frequency deleterious SNV rs2228570 (start lost of VDR) has been reported to contribute to hypertension, and also protects from intervertebral disc degeneration." (PMID 29420653, 2018). "Briefly, experimental studies have shown elevated production of renin and angiotensin II in vitamin D receptor (VDR) knockout mice, leading to hypertension and cardiac hypertrophy." (PMID 30057603, 2018). "Serum 25(OH)D and VDR in children with hypertension were lower than those in the control group in univariate and multivariate regression analyses." (PMID 30631592, 2018). "Earlier animal studies demonstrated that vitamin D receptor-null (VDR-null) mice have a several-fold increase in renin expression and plasma angiotensin II production, which leads to hypertension, cardiac hypertrophy and increased water intake." (PMID 29977597, 2018). "In the cardiovascular system, VDR deletion results in elevated production of renin and angiotensin II, leading to hypertension and cardiac hypertrophy." (PMID 28912809, 2017). "Third, the VDR knock-out mouse has been shown to suffer from hypertension and congestive heart failure, further supported by the VDR mediated downregulation of the expression of renin, which is one of the major determinants in cardiovascular risk." (PMID 28390010, 2017). "We have shown how olmesartan, a drug marketed for mild hypertension, acts as a high-affinity partial agonist for the VDR, and that it seems to reverse disease activity resulting from VDR dysfunction." (PMID 27412293, 2017). "The global VDR knockout mice also develop alopecia, hypertension, impaired insulin secretion, skeletal muscle fiber atrophy with motor deficits, left ventricular hypertrophy and failure, and cardiac fibrosis." (PMID 28390010, 2017). "Mitochondrial dysfunction has been implicated in the etiology of many diseases, like hypertension, and, among the many factors involved, our laboratory has characterized in mitochondria the RAAS exaltation and deficiency of vitamin D receptor." (PMID 27009470, 2016). "Among lead workers with the VDR Bsm1 variant, SBP were 2.7-3.7 mmHg higher and prevalence of hypertension was higher (OR =2.1)." (PMID 25582168, 2015). "Recently, chronic vitamin D receptor stimulation by cholecalciferol therapy has been shown to blunt systemic RAS activity in essential hypertensive patients with hypovitaminosis D under constant salt intake and free from drugs interfering with RAS." (PMID 26000281, 2015). "In vitamin D receptor knock-out mice renin expression is highly increased leading to hypertension and LV hypertrophy and in mice active vitamin D analogue treatment suppresses renin expression, independent of PTH." (PMID 24661355, 2014). "Renin expression is highly elevated in VDR null mice, which leads to systemic hypertension, cardiac hypertrophy and heart failure." (PMID 23889806, 2013). "Thus, the regulation of VDR expression is vital for the hormonal actions of vitamin D. Deficiency of vitamin D has been linked with increased risk of cardiovascular disease-related mortalities including hypertension, congestive heart failure, peripheral arterial disease, and myocardial infarction." (PMID 22880111, 2012). "It is therefore unlikely that previous associations of some of the current candidates genes (VDR, FGB, AGTR1 and GPX1) with hypertension, have influenced our results, although this cannot be completely excluded." (PMID 22879966, 2012). "Since we observed a correlation between VDR levels and hypertension (already known in literature), we corrected the analyses also by this variable in a second step, confirming a significant decrease of VDR mRNA in both DPN and CAN groups (pcorr = 0.024 and pcorr = 0.027, respectively)." (PMID 39976627, 2025).
Hypertension (continued). "These compelling findings conclusively establish that the secretion of macrophage-derived miR-106b-5p, resulting from impaired VDR signaling, substantiates macrophage infiltration within renal vasculature, thereby contributing to inflammation-induced hypertension." (PMID 40585349, 2025). "Unfortunately, our study did not evaluate the association of vitamin D and VDR SNPs with indicators such as body mass index (BMI), hypertension, vitamin D supplementation, or seasonality; therefore, further studies are needed." (PMID 38397449, 2024). "In this regard, vitamin D receptor knockout mice develop severe hypertension and, conversely, vitamin D receptor agonists (VDRAs) such as paricalcitol lower blood pressure in conjunction with inhibitors of the renin-angiotensin-aldosterone system (RAAS) in experimental CKD." (PMID 34821697, 2021). "If these same observations occur in humans, hypertension resulting from a VDR-mediated effect may impact on the ESC-like cells within the KALTs that express the RAS and its bypass loops." (PMID 32039229, 2019). "Also, earlier studies demonstrated hypertension and myocardial hypertrophy in vitamin-D receptor knockout mice." (PMID 31635396, 2019). "Moreover, 25(OH)D deficiency was inversely associated with hypertension level, indicating that vitamin D depletion exacerbates hypertension by influencing VDR." (PMID 30631592, 2018). "Although there is also some evidence for a genetic contribution to hypertensive disorders of pregnancy, a recent case-control study found the three common VDR SNPs (FokI, ApaI and BsmI) equally distributed in gestation hypertension groups compared with healthy pregnancy cohort." (PMID 29113124, 2017). "Moreover, the linkage disequilibrium observed between BsmI and TaqI suggests that these polymorphisms may exert combined effects, yet BsmI appears to play a more dominant role in modulating the VDR’s influence on hypertension." (PMID 39715198, 2024). "Importantly, VDR and 1α-hydroxylase knockout mice developed arterial hypertension and myocardial hypertrophy, even after calcium homeostasis was restored; however, blocking the RAAS with angiotensin-converting enzyme inhibitors normalized BP and cardiac abnormalities." (PMID 36788562, 2023). "Therefore, it is hypothesized that the reduced levels of vitamin D and VDR observed in keloids may weaken the regulatory effect of vitamin D on the renin–angiotensin system (RAS), thereby promoting the development of hypertension and potentially increasing the risk of keloid formation." (PMID 40836860, 2025). "Briefly, the kidney cells responsible for renin production (juxtaglomerular cells) are sensitive to calcitriol, and VDR and CYP27B1 knock-out mice develop high renin systemic hypertension which can be rescued with angiotensin converting inhibitors." (PMID 40448712, 2025). "Studies with vitamin D receptor (VDR) knockout mice show an increased renin–angiotensin–aldosterone system (RAAS) activity and increased hypertension, suggesting a key role for vitD as a potential antihypertensive agent." (PMID 36902110, 2023). "Inactivation of VDR results in an increase in RAS activity, endothelial dysfunction, hypertension, and cardiac hypertrophy." (PMID 36882686, 2023). "Hypertension is pathologically related to hyperactivity of the renin-angiotensin system (RAS), and animal studies show the involvement of VDR activation in downregulating RAS." (PMID 35147511, 2022). "In the mice, in fact, with null vitamin D receptor (VDR-null) the expression of renin and angiotensin II has increased and it leads to hypertension, cardiac hypertrophy, and an increase in the intake of water." (PMID 36313775, 2022). "In conclusion, VDR and MEGALIN gene variations can affect the prevalence of MetS and the incidence of hypertension in a sex-specific manner, respectively, among African-American urban adults." (PMID 29795187, 2018).